LCN2 (lipocalin 2)
Diseases named in the same sentence as LCN2 in open-access papers (continued):
Sharing a sentence is not in itself a finding about the gene and the disease.
prostate carcinoma (continued). "Induction of ER stress using thapsigargin (Tg), a canonical pharmacologic ER stress inducer, or via glucose deprivation, a physiologic ER stressor present in the tumor microenvironment, upregulates LCN2 production in murine and human prostate cancer cells." (PMID 21649922, 2011). "Here we establish a link between the ER stress response in prostate cancer cells and Lcn2 upregulation." (PMID 21649922, 2011). "With the exception of work showing that the LCN2/MMP9 complex is more likely to be found in the urine of prostate cancer patients than controls, little is known about LCN2 in prostate cancer." (PMID 21649922, 2011). "Inhibition of NF-κB in prostate cancer cells undergoing Tg-mediated ER stress by BAY 11-7082 abrogates Lcn2 upregulation." (PMID 21649922, 2011). "To extend these findings to human prostate cancer, we interrogated LCN2 activation during conditions of ER stress in two human prostate cancer cell lines, LNCaP and PC3." (PMID 21649922, 2011). "We conclude that the UPR activates Lcn2 production in prostate cancer cells in an NF-κB-dependent manner." (PMID 21649922, 2011). "Taken together, these results indicate that the ER stress response drives transcription of LCN2 and pro-inflammatory cytokines in human prostate cancer cells." (PMID 21649922, 2011). "Taken together, these data indicate that ER stress in murine prostate cancer cells drives the NF-κB-dependent transcription of Lcn2 and pro-inflammatory cytokines." (PMID 21649922, 2011). "Moreover, LCN2 promotes cell migration and invasion of prostate cancer by inducing epithelial-to-mesenchymal transition via the extracellular signal-regulated kinase (ERK)/SLUG pathway." (PMID 39941741, 2025). "IL-1β expression has been reported to be closely related to LCN2 levels in prostate cancer cells." (PMID 40109857, 2025). "Moreover, in vitro studies have shown that LCN2 plays a positive role in the progression of prostate cancer." (PMID 40109857, 2025). "Additionally, Navin R Mahadevan reported that ER stress drives LCN2 upregulation in prostate cancer cells." (PMID 39850877, 2024). "Moreover, another study showed that LCN2 promoted the invasion of prostate cancer cells, and enhanced SLUG expression through activation of ERK signaling pathway." (PMID 34969358, 2022). "Since LCN2 could facilitate cell proliferation of castration-resistant prostate cancer via androgen receptor, LCN2 could be a novel target in cancer therapy." (PMID 35327169, 2022). "Consequently, it is clear that further studies are needed to evaluate the predictive and prognostic role of lipocalin-2 in prostate cancer patients." (PMID 33542838, 2021). "In addition, in the xenograft prostate cancer model, lipocalin-2 overexpression has significantly promoted tumor growth." (PMID 33542838, 2021). "The UPR activates lipocalin 2 production in prostate cancer cells." (PMID 32093767, 2020). "We here show that the homologous nucleoside antibiotic tunicamycin blocks N-linked glycosylation but not secretion of LCN2 in primary murine hepatocytes, derivatives thereof, human lung carcinoma cell line A549, and human prostate cancer cell line PC-3." (PMID 29755357, 2018). "Knockdown of LCN2 suppresses the invasion of prostate cancer cells through downregulation of MMP-9." (PMID 26840566, 2016). "Thus, we found that NF-κB activation directly precedes the transcriptional activation of Lcn2 and that of pro-inflammatory cytokines, suggesting that Lcn2 transcription is part of an UPR-mediated inflammatory program in prostate cancer cells." (PMID 21649922, 2011). "If our prediction turns out to be correct, we anticipate that Lipocalin 2 could serve as a novel biomarker of prostate cancer progression." (PMID 21649922, 2011). "Thus, LCN2 is potentially an interesting therapeutic target for the therapy of prostate cancers." (PMID 35053376, 2022).
prostate carcinoma (continued). "These inhibitors could be tested in other diseases that involve NGAL, such as metabolic and cardiovascular diseases or cancer, such as breast or prostate cancers, for which genetic Lcn2 inactivation and NGAL-neutralizing antibodies have proven to be beneficial." (PMID 33510370, 2021). "LCN2 knockdown in PC3 and DU145 prostate cancer cells decreased cell proliferation, colony formation, cell cycle arrest, migration, and invasion." (PMID 39941741, 2025). "Slug is also upregulated by LCN2 in an ERK signalling-dependent manner, promoting prostate cancer cell invasion and migration." (PMID 40109857, 2025). "Previous studies have shown a positive correlation between the invasive capacity of tumor cells and their expression of LCN2, which promotes the epithelial–mesenchymal transition (EMT) and increases the motility and invasiveness of prostate cancer cells." (PMID 34062746, 2021). "LCN2 knockout by CRISPER/Cas9 plasmid decreased cell proliferation and increased sensitivity to cisplatin in prostate cancer cells." (PMID 33144618, 2020). "LCN2 secretion by neutrophils and CXCL1-LCN2 paracrine axis conferred malignant phenotypes to prostate cancer cells via the Src activation and epithelial-mesenchymal transition (EMT)." (PMID 33425761, 2020). "Recent studies showed that ER stress induced by Tg in prostate cancer cells up-regulated lipocalin 2 in an NF-κB-dependent manner, because ER stress inhibition by 4-PBA and NF-κB inhibition by BAY11-7082 inhibited lipocalin 2 induction." (PMID 25514597, 2014). "We demonstrate that the ER stress response in murine and human prostate cancer cells drives the production of Lcn2 in an NF-κB-dependent manner, and that diminishing the UPR dramatically decreases Lcn2 transcription and translation." (PMID 21649922, 2011). "In a co‐culture of osteoblasts (OBs) and BPCa cells, SERPINA3 and LCN2 were remarkably upregulated in BPCa via OB‐derived extracellular vesicles, while they were not in the co‐culture of OBs and osteolytic prostate cancer (LPCa) cells." (PMID 37408474, 2023). "Lipocalin 2 (LCN2) is aberrantly expressed in many cancers including primary prostate cancer (PCa), but its role in CRPC has not been reported." (PMID 27602760, 2016). "Interestingly, LCN2 has also been correlated with disease advancement and appears to modulate several pathways such as the ERK/slug pathway in prostate cancer and the Met/FAK pathway in liver cancer to contribute to EMT progression." (PMID 27912767, 2016). "Additionally, we show here that transcriptional co-repressor CtBP1, which has been shown to repress LCN2 (Lipocalin-2) and ARHGDIB (Rho GDP Dissociation Inhibitor Beta) expression in prostate cancer, regulates miR-124 expression." (PMID 25115393, 2014).
coronary artery disease (46 papers, 2009 to 2025). "High levels of LCN2 are independently associated with a worse risk profile and all-cause mortality of coronary heart disease." (PMID 34938273, 2021). "In addition, another study showed increased Lcn2 expression due to the stress caused by severe hypoxia and ischemic heart disease." (PMID 29755547, 2018). "Here, we investigated whether LCN2 is released from macrophages and contributes to pro-atherosclerotic processes and whether LCN2 plasma levels are associated with the severity of coronary artery disease progression in humans." (PMID 26367277, 2015). "LCN-2 has been observed to be upregulated in conditions such as ischemia–reperfusion, coronary artery disease (CAD), and myocardial infarction." (PMID 39335642, 2024). "For example, Lcn2 is significantly augmented in patients with coronary heart disease and myocardial infarction." (PMID 33530524, 2021). "Circulating levels of LCN2 are augmented andcorrelated closely with the severity of coronary heart disease." (PMID 32696819, 2020). "This study was designed to evaluate the relationship between serum LCN2 levels and coronary artery disease (CAD)." (PMID 24359145, 2013). "Finally, LCN2 plasma levels correlated with the severity of coronary artery disease (CAD) in patients as determined by coronary angiography." (PMID 26367277, 2015).
myocardial infarction (46 papers, 2011 to 2025). Gross necrosis of the myocardium, as a result of interruption of the blood supply to the area, as in coronary thrombosis. "After myocardial infarction, lipocalin-2 (Lcn2)-mediated production of reactive oxygen species (ROS) promotes ventricular arrhythmia." (PMID 37955712, 2024). "Otherwise, LCN2 can exacerbate cardiac dysfunction by suppressing the beneficial cardiac autophagic response and accelerate cardiac apoptosis in myocardial infarction." (PMID 35990970, 2022). "After myocardial infarction, LCN2 produced by neutrophils induces the polarization of macrophages towards a phenotype that allows clearance of apoptotic cells and reduces cardiac fibrosis." (PMID 33214636, 2020). "In addition, different studies reveal that LCN2 levels are significantly increased in patients with CAD and correlate with disease severity and myocardial infarction and therefore might serve as a potential biomarker for cardiovascular events." (PMID 26367277, 2015).
Alzheimer disease (45 papers, 2010 to 2025). A progressive, neurodegenerative disease characterized by loss of function and death of nerve cells in several areas of the brain leading to loss of cognitive function such as memory and language. "Many studies have linked the expression of LCN2 to Alzheimer’s disease, Parkinson’s disease, and multiple sclerosis." (PMID 39125762, 2024). "Plasma Lipocalin-2 has potential as a diagnostic biomarker for Alzheimer’s disease and seems to be independent from currently employed biomarkers." (PMID 35027079, 2022). "LCN2 deficiency significantly reduces hippocampal iron accumulation associated with Alzheimer’s disease, which may alleviate the aggregation of pathogenic proteins such as Aβ caused by elevated iron levels." (PMID 41007258, 2025). "Furthermore, besides inflammation, LCN2 was connected to neurodegenerative diseases, especially Alzheimer disease, while NLRP3 was associated with multiple sclerosis." (PMID 37240031, 2023). "In the CNS, LCN2 is associated with Alzheimer’s disease pathology in human postmortem brain." (PMID 31269059, 2019). "Increased levels of lipocalin-2 considered together with its iron transport abilities may partially explain the accumulation of iron in brain associated with Alzheimer’s disease, Parkinson’s disease and multiple sclerosis." (PMID 23593384, 2013). "Moreover, among the genes that were modulated by exposure to METH, Lcn2 is involved in lipid metabolism, inflammation, iron transport and infections and Ptpn6, a protein tyrosine phosphatase, that is involved in adaptive and innate immunity and has been linked to Alzheimer’s Disease as risk factor." (PMID 40143289, 2025). "Clinical studies have further shown that Lcn2 expression is significantly elevated in hippocampal injury and in ischemic and neurodegenerative conditions such as Alzheimer's disease." (PMID 37864452, 2024). "Recent studies have investigated the effects of Lcn2 on Alzheimer’s disease, spinal cord injury, perioperative neurocognitive disorders, and diabetic retinopathy." (PMID 37672148, 2024). "It has been shown that the expression of LCN2 is increased under conditions of neuroinflammation in the brain, such as Alzheimer's disease." (PMID 38685046, 2024). "Another predominant finding is the involvement of LCN2 in the periphery and brain in different central nervous system (CNS)-related conditions such as Alzheimer’s disease, Parkinson’s disease, and vascular dementia." (PMID 38673873, 2024). "In humans, Lcn2 has previously been shown to distinguish VaD from other kinds of dementia such as Alzheimer’s disease dementia." (PMID 37175797, 2023). "On the other hand, others have proposed LCN2 as a biological marker for disease progression in neurodegenerative disorders such as Alzheimer’s disease and multiple sclerosis." (PMID 37168715, 2023). "LCN2 has been proposed as a biomarker for preclinical Alzheimer’s disease and vascular dementia; its usage as a potential biomarker for PD still needs to be further explored." (PMID 36189230, 2022). "Several clinical studies have assessed the potential value of LCN2 as a biomarker for neurodegenerations including vascular dementia, mild cognitive impairment or preclinical stage of Alzheimer’s disease." (PMID 35413913, 2022). "Plasma Lipocalin-2 was significantly lower in Alzheimer’s disease compared to healthy controls (p < 0.001) and all other groups (p < 0.01) except for mixed dementia (vascular and Alzheimer’s pathologic changes)." (PMID 35027079, 2022). "Plasma Lipocalin-2 has been proposed as a biomarker for Alzheimer’s disease but available data is scarce and inconsistent." (PMID 35027079, 2022). "Although many studies have investigated the mechanism of LCN2 in brain injuries, the effect of LCN2 on amyloid-toxicity-related memory deficits in a mouse model of Alzheimer’s disease (AD) has been less studied." (PMID 34829528, 2021).
Alzheimer disease (continued). "Lcn2 is also upregulated in the brain of patients affected by Alzheimer’s disease, Parkinson’s disease, and multiple sclerosis." (PMID 34136483, 2021). "LCN2 was significantly elevated in VaD compared to controls, Alzheimer’s disease (AD), other neurodegenerative dementias, and cognitively unimpaired patients with cerebrovascular disease." (PMID 32001681, 2020). "Recently, Lcn2 has emerged as an important component of pathophysiology of several disorders, including Alzheimer’s disease (AD), Parkinson’s disease, multiple sclerosis and depression." (PMID 33105802, 2020). "Interestingly, elevated levels of mRNA and protein of LCN2 have been observed in the affected brain regions of individuals with Alzheimer’s disease." (PMID 38673873, 2024). "Peripheral LCN2 has been evaluated and established as a biomarker for kidney injury but was also proposed as a potential blood-based biomarker for intestinal inflammation and Alzheimer’s disease." (PMID 35027079, 2022). "Thus, we evaluated plasma Lipocalin-2 in the context of Alzheimer’s disease, differential diagnoses, other biomarkers, and clinical data." (PMID 35027079, 2022). "Lipocalin-2 (LCN2), which is secreted by various cell types, is associated with several metabolic diseases and brain injuries such as ischemic brain disease, diabetic encephalopathy, and Alzheimer’s disease (AD)." (PMID 35884685, 2022). "Furthermore, clinical studies have revealed that Lcn2 levels in plasma and cerebrospinal fluid can be used as biomarkers for Alzheimer’s disease and other neurodegenerative dementias." (PMID 34136483, 2021). "Importantly, the immune-response genes of Lcn2, S100a8, and S100a9 have been found that markedly increased in the patients’ hippocampus with Alzheimer's disease." (PMID 34565419, 2021). "Recently, LCN2 was also found to be involved in the pathogenesis of Alzheimer’s disease." (PMID 32605546, 2020). "Furthermore, the measurement of cerebrospinal fluid Lcn2 levels might be able to diagnose brain damage due to Alzheimer’s disease, traumatic brain injury and chronic stress." (PMID 31936294, 2020). "Our results highlight a shared neuroinflammatory signature across Alzheimer’s disease (AD), Parkinson’s disease (PD), and Huntington’s disease (HD), characterized by the dysregulation of hub genes such as MMP9, S100A8, S100A9, CCL2, and LCN2." (PMID 41614741, 2025). "For example, in J20 Alzheimer’s disease mouse model, Lcn-2 did not significantly impact glial cell activation." (PMID 38533497, 2024). "Another study validated the finding that a lack of LCN-2 significantly reduced Alzheimer’s disease-related hippocampal iron accumulation." (PMID 35493318, 2022). "Interestingly, Lipocalin 2 was lower in patients with rapid disease course compared to patients with non-rapidly progressive Alzheimer’s disease (p = 0.013)." (PMID 35027079, 2022). "In a clinical study that enrolled 41 patients with mild cognitive impairment (MCI), 62 patients with Alzheimer's disease and 38 healthy elderly control subjects, it was found that MCI, which is a prodromal-inflammation stage of Alzheimer's disease, is correlated with elevated plasma LCN2 levels." (PMID 27729871, 2016).
Hyperglycemia (42 papers, 2008 to 2026). An increased concentration of glucose in the blood. "Furthermore, STZ-induced hyperglycemia increased the expression of Tnf-α and Il-6 mRNA in the hippocampus of diabetic mice, whereas the expression levels of these cytokines were significantly attenuated in the Lcn2-deficient mice." (PMID 30761088, 2019). "The expression of LCN2 at the protein level was assessed, and the results on whether hyperglycemia augmented LCN2 expression were inconsistent, a limitation of our study." (PMID 37371057, 2023). "Taken together, these results suggest that the TonEBP may transcriptionally regulate systemic and neuroinflammation via the direct binding to position − 2827 of the LCN2 promoter region under diabetic conditions of low-grade inflammation and hyperglycemia." (PMID 34844610, 2021). "In addition, the hyperglycemia-induced increase in expression of pro-inflammatory cytokines was significantly attenuated in Lcn2 KO mice." (PMID 30761088, 2019). "Besides, hyperglycemia has been recently shown to induce an increase expression of pro-inflammatory lipocalin-2 (LCN2) in DRG SGCs, potentiating neuroinflammation and neurotoxicity via LCN2-pyruvate dehydrogenase kinase isoform 2 (PDK2)-lactic acid pathway contributing to the progression of DPN." (PMID 38236305, 2024). "Therefore, the control of hyperglycemia-induced expression of LCN2 or its activity in the hippocampus may be important for neuroprotection in these patients." (PMID 30761088, 2019). "Moreover, the strong correlation between serum lipocalin-2 levels and both the HOMA-IR index and plasma glucose levels, which is not affected after adjusting for the BMI, suggests that lipocalin-2 might represent an independent risk factor for development of IR and hyperglycemia." (PMID 21143924, 2010).